EPCAM (epithelial cell adhesion molecule)
Diseases named in the same sentence as EPCAM in open-access papers (continued):
Sharing a sentence is not in itself a finding about the gene and the disease.
cancer (continued). "EV membrane-associated proteins, including NY-ESO-1, EGFR and EpCAM, have been found to have prognostic value in cancer patients." (PMID 33260345, 2020). "Among the 99 malignant neoplasms, only 19 (19/99; 19.2%) showed a complete loss of EPCAM expression, and 10 (10/99; 10.1%) were informative and corresponded to CRC, all belonging to patients with EPCAM 3′-end deletions." (PMID 33003511, 2020). "Cancer stemness markers such as ALDH1/A2, CD44, CD166 and EpCAM are associated with drug resistance in cancers." (PMID 32899896, 2020). "The authors showed that natural or experimental (knock down) loss of EpCAM reduced the proliferation rate, but promoted cancer cell migration and invasion." (PMID 32764280, 2020). "Nevertheless, several studies have demonstrated either reduced or loss epithelial markers expression such as EpCAM and cytokeratin as the cancer cells undergo the epithelial-mesenchymal transition (EMT) during the metastasis process." (PMID 32046162, 2020). "Radioresistance was found to be associated with increased cancer stem cells (CSCs), and elevated EpCAM expression in the cell population." (PMID 33490064, 2020). "Clinical studies on the predictive potential of EpCAM for carcinoma entities associated with a high degree of treatment resistance are required for the use of EpCAM as biomarker in clinical decision-making." (PMID 32507912, 2020). "Epithelial cell adhesion molecule (EpCAM) is a membrane glycoprotein associated with cell–cell adhesions and is involved in cell proliferation in different cancers." (PMID 31286981, 2019). "This knowledge will open new avenues for the use of EpCAM as a diagnostic liquid biopsy marker in cancer patients." (PMID 31225512, 2019). "Isolation is generally accomplished by antibodies directed toward a single carcinoma-associated antigen, typically epithelial cell adhesion molecule (EpCAM)." (PMID 31581693, 2019). "Because EpCAM expression is limited to normal and malignant epithelia, it has been used as diagnostic marker for the detection of carcinoma cells in mesenchymal organs such as blood, bone marrow or lymph nodes." (PMID 31225512, 2019). "EpCAM has also been shown to be linked to cellular signaling via the Wnt pathway, resulting in an ability to potentiate cancer stem cell (CSC) features." (PMID 30116994, 2018). "Although EpCAM is one of the best studied cancer-associated antigens, its expression profile, biological function and clinical significance in NPC have not been reported until now." (PMID 29305578, 2018). "Cancer cells exhibit a decreased expression of anchor proteins such as E-cadherin and beta-catenin, a loss of cytokeratins and EpCAM (epithelial cell adhesion molecule) with upregulation of mesenchymal markers such as vimentin, N- and O-cadherins." (PMID 30180883, 2018). "During these studies, a clinical proteomics analysis using resected biopsies from patients with esophageal adenocarcinoma identified AGR2 and EpCAM as highly expressed in primary adenocarcinoma as well as cancer-associated lymph nodes." (PMID 29339412, 2018). "The proof of principle was additionally confirmed using cancer-cell-associated marker epithelial cell adhesion molecule (EpCAM) in nanoengineered MSC and MCF7 co-culture." (PMID 29515946, 2018).
cancer (continued). "Mounting data from recent years have indicated that EpCAM is a useful biomarker for the identification and isolation of subsets enriched for CSCs, or is associated with the “stemness” in various cancers, including CaP." (PMID 30419852, 2018). "EpCAM is a tumor-associated antigen that is highly expressed on epithelial cancers and their associated cancer stem cells." (PMID 29301363, 2018). "The epithelial cell adhesion molecule (EpCAM), or CD326, was one of the first cancer associated biomarkers to be discovered." (PMID 29329202, 2018). "The epithelial cell adhesion molecule, EpCAM, was one of the first cell surface markers to be associated with cancer and has been associated with a poor prognosis in a number of different cancer subtypes." (PMID 30586898, 2018). "These un-polarized single or small groups of carcinoma cells exhibit loss of E-cadherin and EpCam, but upregulated nuclear β-catenin and cytoplasmic laminin-5γ2 corresponding to the changes found in EMT." (PMID 30361805, 2018). "Several studies have demonstrated that EpCAM or CD13 as stemness markers are associated with a poor prognosis in various types of cancer." (PMID 28572700, 2017). "EpCAM-positive cancer cells have been demonstrated to associate with increase self-renewal and tumorigenesis capacities." (PMID 28851352, 2017). "EpCAM is expressed on epithelial cells, is highly up-regulated in epithelial carcinomas, and is associated with cancer progression and metastases." (PMID 28968987, 2017). "Of the cancer-related genes, 44 were found to have mutations in the analyzed cells, indicating that EpCAM/CK-positive cells have a malignant tendency." (PMID 28842574, 2017). "EpCAM is an epithelial surface molecule whose expression in RCC is an independent predictor associated with improved survival, while in several cancers, EpCAM is considered as a progression/CSC marker." (PMID 26551931, 2016). "The down-regulation of EpCAM by Z3, Z5, CM and warfarin was confirmed by western blotting, and caused inhibition on adhesion of cancer cells to human endothelial cells." (PMID 27480614, 2016). "We then analyzed the association between EpCAM expression on CTCs and characteristics of the patients' cancers." (PMID 27013581, 2016). "EpCAM is currently used as pan-cancer marker and their expression is also associated with stem cells." (PMID 27127176, 2016). "Epithelial cell adhesion molecule (EpCAM) has been found to be over-expressed during stages of carcinogenesis and has been associated with poor overall survival in many cancers." (PMID 26984381, 2016). "Of note, the WM130-induced reduction of cancer stem-like cells (EpCAM/CD133 positive) appeared to be associated with the suppression of self-renewal capability and the promotion of differentiation from CSCs to hepatocytes." (PMID 27783993, 2016). "Overexpression of EpCAM has been associated with more malignant biological phenotypes as a reflection of the evasive pluripotent cancer stem cell population and worse survival." (PMID 27447573, 2016). "EpCAM overexpression was associated with protective or promoting roles in patients with different cancer types." (PMID 26942873, 2016). "EpCAM is a pan-epithelial differentiation carcinoma-associated antigen expressed on almost all carcinomas." (PMID 26984381, 2016). "Epithelial cell adhesion molecule (EPCAM; also known as TACSTD1 or CD326) expression in carcinoma cells has significance as a potential diagnostic and therapeutic target." (PMID 26528695, 2016). "Increasing clinical evidence has confirmed that EpCAM is involved in cancer progression and is associated with a poor prognosis." (PMID 26356670, 2015).
cancer (continued). "CD326 (epithelial cell adhesion molecule; EpCAM) was originally the epithelial cell marker, and it has been reported to be expressed by approx. 87–100 % of the main ascites-causing carcinomas." (PMID 26702369, 2015). "The Epithelial cell adhesion antigen EpCAM (gene name TACSTD1) has been identified as tumour associated antigen on carcinomas of various origins." (PMID 26296970, 2015). "This paradoxical association of EpCAM expression with prognosis in different cancers is supported by functional studies of EpCAM biology using in vitro and in vivo cancer models as well." (PMID 25265904, 2014). "Existing literature has implicated many of these miRNA regulated by EpCAM in various types of cancers; it is likely that these miRNAs have a strong role in common cancer pathways." (PMID 25502397, 2014). "Further functional studies are needed to elucidate the effects of the genetic variants on the functions of EPCAM in the development of cancer." (PMID 24718422, 2014). "The promotion of carcinogenesis and metastasis by carcinoma-specific complexes, comprised of EpCAM with CD44 variants and claudin-7, has been demonstrated in several malignancies." (PMID 24727741, 2014). "Genetic alteration and morphological changes are modulated during cancer metastasis, such as loss of epithelial cell identity (e.g., occludin and EpCAM) and acquisition of mesenchymal features (e.g., vimentin and TWIST1)." (PMID 24039787, 2013). "Initially described as a tumor-associated antigen, EpCAM is highly expressed in gastrointestinal, lung, prostate, breast, ovarian, and other cancers of epithelial origin." (PMID 23320927, 2013). "Of the 194 individuals with an EPCAM mutation included in their studies, 16 developed cancers other than colonic or endometrial [duodenal: n=3; and pancreatic: n=4; were the most common]." (PMID 23938213, 2013). "Although EpCAM belongs to the best studied cancer-associated antigens, its biological role in tumorigenesis is still not fully understood." (PMID 23830302, 2013). "The tumour-associated antigen EpCAM (Epithelial Cell Adhesion Molecule) is a single transmembrane protein, which is highly and frequently expressed in human and rodent carcinomas, tissue progenitors, embryonic and adult stem cells." (PMID 24009667, 2013). "One inconsistency in the literature is that EpCAM expression in primary cancer specimens appears to be associated with a favorable prognosis in some cancer types, and an unfavorable prognosis in other cancer types." (PMID 22132731, 2011). "EpCAM serves important roles in cell adhesion, proliferation, differentiation, migration, cell cycle regulation and is implicated in cancer and stem cell signaling." (PMID 20579375, 2010). "EpCAM is a well-established carcinoma marker that in addition to its diagnostic value for rapidly growing tumors of epithelial origin is used as a potential target for immunotherapy." (PMID 19609345, 2009). "Consequently, EpCAM serves as a potential molecular link underlying the comorbidity between neuropsychiatric disorders and cancers." (PMID 40508038, 2025). "It obstructs the nuclear translocation of β-catenin, thereby inhibiting the proliferation of well-differentiated HepG2 and HEK293 cancer cells while also diminishing the proportion of EpCAM + CSCs associated with cancer stemness and tumour progression (In vivo, Mice, i." (PMID 40926993, 2025). "EpCAM is associated with increased vascularization, cancer stemness, and poor survival." (PMID 40377687, 2025). "Mechanistically, CD44v6 influenced the expression of key CSC markers, including CD24, CD133, and EpCAM, which are known to be associated with cancer progression, stemness, and malignant behaviors like self-renewal, proliferation, migration, and chemoresistance." (PMID 40069421, 2025).
cancer (continued). "Indeed, the unfavorable prognosis associated with elevated EpCAM expression in numerous cancer types is linked to EpCAM’s capacity to modulate fundamental biological processes, including cell differentiation, proliferation, migration, and invasion." (PMID 39456890, 2024). "Enriched CTCs were then analyzed in three steps by flow cytometry: (i) removing dead cells, (ii) isolation of CD45(−) PanCK(+) cells as CTCs, and (iii) analysis of CTCs producing CD90, CD133, EpCAM, or vimentin, which are proteins associated with cancer progression." (PMID 39108869, 2024). "Notably, DF5 markedly affected the CD133+EpCAM+ cancer stem-like PC cell subpopulation, associated with drastic effects on cell clonogenicity." (PMID 36768301, 2023). "Although it has been shown to be overexpressed in a wide variety of epithelial tumors, EpCAM seems to be associated with a poor prognosis in certain cancer types (colorectal, breast, prostate, gallbladder, ovarian, bladder, pancreas, and adenoid cystic carcinomas)." (PMID 37175871, 2023). "Based on this observation, we anticipate that cancer-associated EpCAM mutations that cause loss of membrane localization may a play significant role in contributing to cancer cell growth and EMT." (PMID 37192201, 2023). "The consideration of EpCAM-mediated resistance development in radiation therapy may prove valuable for assessing the risk of local recurrence in cancer patients." (PMID 37784157, 2023). "In other cancer types, EpCAM expression is associated with improved outcomes." (PMID 37192201, 2023). "To achieve an OC-directed blockade of the CD73/ADO immune checkpoint, we engineered a novel tetravalent bsAb, designated bsAb CD73xEpCAM, that selectively binds to the pan-carcinoma-associated cell surface antigen ‘Epithelial Cell Adhesion Molecule’ (EpCAM) and concurrently blocks CD73." (PMID 37509310, 2023). "EPCAM overexpression has been linked to promoter hypomethylation EPCAM-negative cells treated with a DNA methyltransferase inhibitor prompted EPCAM expression in various cancers types including ovarian cancer." (PMID 35523936, 2022). "EpCAM expression has been associated with the stem cell-like properties of cancer cells." (PMID 35361871, 2022). "A few studies have reported the presence of CD45+EpCAM+ double-positive cells in cancer, but the underlying mechanism remains unclear with respect to how these cells originate and their function in cancer biology." (PMID 35711455, 2022). "Together, these data demonstrate that live, attenuated mycobacteria from clinical-grade BCG were able to directly infect a subset of human cancer cells and that this intracellular infection was associated with a significant diminution of HLA-I and EpCAM membrane expression." (PMID 35503263, 2022). "The aptamer-linked quantum dots (QDs-Apt) that could bind to the cancer biomarker protein epithelial cell adhesion molecule (EpCAM) was the donor and Cy3-labeled complementary DNA (cDNA) was the acceptor." (PMID 36296141, 2022). "Supporting the EpCAM expression results, Smurf2 knockdown was associated with the increase in the sphere formation rate, indicating that a decrease in Smurf2 expression increased the stem cell-like properties of cancer cells." (PMID 35361871, 2022). "The expression of EpCAM in variant cancers is quite different." (PMID 33919456, 2021). "To investigate the role of cancer-associated EpCAM mutations, we initially focused on C66Y." (PMID 33980181, 2021).
cancer (continued). "We identified multiple cancer-associated mutations which may affect the overall structure and function of EpCAM." (PMID 33980181, 2021). "To date, over 130 coding, cancer-associated mutations in the EpCAM gene have been identified." (PMID 33980181, 2021). "Taken together, our findings and these recent preclinical studies suggest that CTSL inhibition in cancers harboring EpCAM mutations may prove to be an effective strategy." (PMID 33980181, 2021). "Predisposition to the early onset of certain types of primary cancers may be caused by germline mutations in DNA mismatch repair (MMR) genes or deletions in the EPCAM gene." (PMID 34523816, 2021). "Therefore, the results on the effect of EpCAM expression on cell migration and invasion are also conflicting in cancer cell lines, and this seems intrinsically linked with the biphasic effects of EpCAM on cell EMT regulation." (PMID 33691694, 2021). "EpCAM is an important marker of the cancer stem cells that are the major cause of metastasis." (PMID 34790117, 2021). "Cancers harboring cancer-associated EpCAM mutations and/or EpCAM silencing may have increased CTSL activity." (PMID 33980181, 2021). "In an era where genomic testing is being increasingly used to drive biomarker-driven therapeutic decisions in patient care, additional study is required to understand the role of EpCAM mutations in cancer biology, and the potential to target these mutations with existing and/or novel therapies." (PMID 33980181, 2021). "Generally, EpCAM biomarker is closely associated with cancer cell proliferation and migration, thus development of DDSs which target the EpCAM receptors may lead to reduction of cancer cell metastasis." (PMID 34641857, 2021). "In addition to these nonsynonymous mutations, EpCAM expression is often silenced in cancer cells by promoter methylation, histone modification, and/or aberrant transcription factor signaling." (PMID 33980181, 2021). "EpCAM can be used as a prognostic factor for multiple cancers; interestingly, high expression for some cancers (such as breast) is associated with poor clinical outcomes, whereas the inverse is true for other cancers (such as thyroid cancer)." (PMID 34439139, 2021). "During the last three decades, an expanding body of research has demonstrated that EpCAM has many versatile functions that have important implications for cancer initiation, progression, and the underlining mechanisms of epithelial-to-mesenchymal transition (EMT)." (PMID 34209658, 2021). "EpCAM has been implicated in the regulation of cancer invasion." (PMID 33980181, 2021). "This rather broad definition has been shown to be incomplete as potentially highly relevant circulating cancer-associated cells might lack EpCAM, or even co-express CD45 and other macrophage/myeloid or stem-cell markers." (PMID 32182935, 2020). "Moreover, EpCAM expression is linked to CSC features in various forms of cancer such as gastric, prostate, pancreatic and breast." (PMID 33225916, 2020). "A loss or a decrease in EpCAM expression and an increase in mesenchymal markers such as N-cadherin, vimentin, and podoplanin in cancer cells may accompany the EMT." (PMID 32071283, 2020). "Therefore, the prognostic value of EpCAM expression is intrinsically associated with the cancer type and/or subtype." (PMID 32764280, 2020). "Further investigations are necessary to confirm these data suggesting that EpCAM in circulation may represent a cancer-specific or at least cancer-associated exosomal biomarker." (PMID 31225512, 2019). "Furthermore, although EpCAM is an antigen expressed on epithelial cell surface, its expression is known to be attenuated in cancer cells, which causes EMT, leading to the inability to identify CTCs using CellSearch®." (PMID 31416266, 2019). "Notably, a series of researches has suggested that EpCAM can be used as diagnostic or prognostic biomarkers for various cancers." (PMID 31886299, 2019).